RN7SL343P (RNA, 7SL, cytoplasmic 343, pseudogene)
Gene: Miscellaneous RNA gene on chromosome 9 (42,011,350 to 42,011,610, forward strand). Ensembl gene ENSG00000273717.
Homologues: Orthologues: chimpanzee Metazoa_SRP (99% identical). Paralogues in human: RN7SL462P (100% identical), RN7SL640P (100% identical), RN7SL422P (99% identical), RN7SL2 (82% identical), RN7SL3 (82% identical), RN7SL1 (81% identical), RN7SL464P (80% identical), RN7SL607P (79% identical), RN7SL597P (79% identical), RN7SL804P (79% identical), RN7SL655P (79% identical), RN7SL543P (78% identical), and 705 more.